RNU7-197P (RNA, U7 small nuclear 197 pseudogene)
Gene: Small nuclear RNA gene on chromosome 4 (148,991,572 to 148,991,633, reverse strand). Ensembl gene ENSG00000239168.
Homologues: Orthologues: chimpanzee U7 (100% identical), macaque U7 (95% identical). Paralogues in human: RNU7-48P (82% identical), RNU7-136P (81% identical), RNU7-103P (79% identical), RNU7-172P (79% identical), RNU7-183P (79% identical), RNU7-2P (79% identical), RNU7-30P (79% identical), RNU7-82P (79% identical), RNU7-88P (79% identical), RNU7-1 (77% identical), RNU7-10P (77% identical), RNU7-124P (77% identical), and 142 more.